BOP1 (BOP1 ribosomal biogenesis factor)
Diseases named in the same sentence as BOP1 in open-access papers (continued):
Sharing a sentence is not in itself a finding about the gene and the disease.
microphthalmia (1 paper, 2022). Congenital or developmental anomaly in which the eyeballs are abnormally small. "Upon bop1 knockdown using the CRISPR/Cas9 system, Xenopus laevis embryos showed eye phenotypes (microphthalmia) and head phenotypes." (PMID 36007075, 2022).
oral carcinoma (1 paper, 2020). "A study revealed that NSUN2 gene copy number was elevated in colorectal and oral carcinoma.We also found that DCAF13 and BOP1 have high copy number gain frequency in patients with LUAD." (PMID 32071816, 2020).
ovarian tumor (1 paper, 2022). "BOP1 was found upregulated in the ovarian tumor and related to strong methylation." (PMID 35222794, 2022).
prostate adenocarcinoma (1 paper, 2021). "It has been reported that higher levels of RSS1 and BOP1 are observed in 14% and 8%, respectively, of prostate adenocarcinomas and that higher levels of RRS1 mRNA correlate with shorter progression-free periods." (PMID 34572914, 2021). "We also analysed which genes encoding the proteins found in the HMGB1 interactomes are more frequently highly expressed in tumour samples from prostate adenocarcinomas, and we found among them RRS1 and BOP1, both important regulators of ribosome biogenesis." (PMID 34572914, 2021).
cancer (23 papers, 2007 to 2025). A tumor composed of atypical neoplastic, often pleomorphic cells that invade other tissues. "Owing to the vital role of BOP1 in cellular biosynthesis, it has been comprehensively evaluated in studies on drug resistance in cancer and the mechanisms underlying tumorigenesis." (PMID 38409361, 2024). "BOP1 has been reported to upregulate in several cancers in recent years, and it is been linked to tumor metastasis, migration, and poor prognosis." (PMID 34603446, 2021). "The results showed that the upregulation of BOP1 is a risk factor in most cancers and is related to DFI, DSS, PFI, and OS." (PMID 34603446, 2021). "DDX24, GTPBP4, and BOP1, for example, are involved in RNA metabolism, cell-cycle regulation, and ribosome biogenesis, respectively, reflecting their substantial influence on cellular processes linked to cancer progression." (PMID 39001461, 2024). "Our results indicate that BOP1 is associated with tumor microenvironment and might be used as a novel prognostic factor in pan-cancer." (PMID 34603446, 2021). "Besides PDPN, many of these molecules, such as IFI6, IFI27, IFI44L, and BOP1, also have been reported to be associated with carcinogenesis and treatment in other types of cancers." (PMID 31321241, 2019). "We also investigated whether BOP1 expression is associated with prognosis of cancer patients." (PMID 34603446, 2021). "It clearly showed that amplification is the most common alteration observed in BOP1, PLAU, SERPINE1, and CKS2 across the cancers, whereas in CCNA2, mutation and deep deletion are prevalent." (PMID 36203433, 2022). "Block of proliferation 1 (BOP1), a nucleolar protein involved in rRNA processing and ribosome assembly, is associated with tumor development in certain cancers of digestive system." (PMID 35222794, 2022). "For example, the present study provided new insights into the involvement of several members of the CanCord34 genes (i.e., EXOSC4, PUF60, and BOP1) in cell viability, cancer stem cell biology, and extracellular communications via secreted plasma vesicles." (PMID 36497066, 2022). "The BOP1 has previously been shown to promote cancer progression phenotypes and the epithelial to mesenchymal transition in several cancer type cell lines." (PMID 36497066, 2022). "Collectively, our findings elucidated that BOP1 has the potential to be a promising molecular prognostic biomarker for predicting poor survival in various malignant tumors, as well as a cancer-promoting gene involved in tumorigenesis and tumor immunity." (PMID 34603446, 2021). "Of these, a positive connection was observed between BOP1 expression and DNA damage repair-related pathways in 29 cancers." (PMID 34603446, 2021). "Of these, the BOP1 expression level was one of the protective elements in LGG, and it was a high-risk factor for the other 13 cancers." (PMID 34603446, 2021). "We found that BOP1 mRNA was upregulated in 25 types of cancer and downregulated in LAML and THCA samples." (PMID 34603446, 2021). "Then, we further analyzed the correlation between the copy number of BOP1 and its expression level in 33 cancers." (PMID 34603446, 2021). "In the present study, we obtained the gene expression data and clinical information from several public databases to assess the expression level and prognostic value of BOP1 in 33 types of cancer." (PMID 34603446, 2021). "In a variety of cancers, BOP1 expression has also been related to the tumor microenvironment, immune cell infiltration, MSI, and TMB, albeit its effect on tumor immunity varies." (PMID 34603446, 2021). "To date, there are no comprehensive studies on the clinical significance and potential biological function of BOP1 in pan-cancer." (PMID 34603446, 2021). "To explore the potential functions of BOP1 in cancers, we conducted a GSEA to analyze which KEGG pathways were associated with BOP1 expression in each tumor." (PMID 34603446, 2021).
cancer (continued). "It is suggested that BOP1 interconnected and interacted with immune cells to promote cancer progression." (PMID 34603446, 2021). "In most cancers, BOP1 expression was shown to be strongly related to the levels of immune cell infiltration." (PMID 34603446, 2021). "Subsequently, we analyzed the correlation of BOP1 expression with the infiltration of 24 immune-related cells in 33 cancers." (PMID 34603446, 2021). "To investigate the prognostic value of BOP1 in human cancers, we used RNA-sequencing data from TCGA to implement a survival analysis for each tumor." (PMID 34603446, 2021). "In conclusion, we performed the first pan-cancer analysis of BOP1, which indicated a substantial difference in BOP1 expression between normal and tumor tissues, as well as a link between BOP1 expression and patient prognosis." (PMID 34603446, 2021). "Then, we investigated the expression of BOP1 in 33 cancer samples from TCGA database and ranked them according to the mean value from low to high." (PMID 34603446, 2021). "Immune cell infiltration is closely related to clinical outcomes of cancer patients.We also evaluated how BOP1 expression correlated with the infiltration of 24 immune-related cells in 33 malignancies." (PMID 34603446, 2021). "Next, we used TCGA and GTEx data to compare the expression of BOP1 between cancer tissues and corresponding normal tissues in 33 cancers." (PMID 34603446, 2021). "We obtained the gene expression data and clinical information from multiple public databases to assess the expression level and prognostic value of BOP1 in 33 cancers." (PMID 34603446, 2021). "We found that BOP1 was altered in 28 cancers, with amplification being the most frequent alteration." (PMID 34603446, 2021). "Previous studies have also clarified that that BOP1 serves as an oncogene in tumorigenesis and progression of certain carcinomas." (PMID 34603446, 2021). "A similar observation was made for deep CNAs in ERGs, namely BOP1 (four cancers), ATAD2 (four cancers), MECOM (three cancers), and PHF20L1 (three cancers)." (PMID 32963031, 2020). "Previous studies on BOP1 have mainly focused on its role in cancer." (PMID 38409361, 2024). "We also evaluated the level of BOP1 in different cancer cells from the CCLE database." (PMID 34603446, 2021). "The expression of BOP1 in various malignancies will result in varied clinical outcomes, necessitating a large number of verification experiments to investigate the particular biological role of BOP1 in each cancer." (PMID 34603446, 2021). "Moreover, it is reported that BOP1 is dysregulated in several cancers and is involved in promoting the tumor occurrence and progression." (PMID 34603446, 2021). "Hence, it is necessary to determine the role of BOP1 in tumor progression, especially in migration and invasion of cancer." (PMID 32167616, 2020). "The analysis revealed a distinct overexpression of a single isoform for several genes, namely AGBL5, BOP1, FTSJ3, LGALS1, and NOP58, suggesting a dominant role of these isoforms in the cancer phenotype." (PMID 39001461, 2024). "For example, BOP1 overexpression confers chemoresistance on TNBC cells via stimulating the WNT signaling and cancer stem cell phenotypes, such as aldehyde dehydrogenase 1A1 (ALDH1A1)." (PMID 36497066, 2022). "Professor Chen confirmed that, in colon cells, lncRNA CCAT2 induces chromosome instability through BOP1-AURKB signals, thus promoting the occurrence of cancer." (PMID 35237659, 2022). "Eventually, taking into account the odds of death from non-neoplastic causes during the follow-up period, we evaluated the connection between BOP1 expression levels and DSS in 33 cancers." (PMID 34603446, 2021). "Considering that MSI is frequently caused by functional defects of the mismatch repair system, and that BOP1 expression is related to mismatch repair, we analyzed the relationship between BOP1 level and MSI in 33 cancer types." (PMID 34603446, 2021).
cancer (continued). "While the endogenous interaction between BRIX1 and BOP1 was observed in cancer cells, the protein levels of BOP1 were not affected by knocking down BRIX1." (PMID 39475053, 2024). "Previous studies have indicated the important role of block of proliferation 1 (BOP1) in the progression of several malignant tumors; no comprehensive pan-cancer analysis of BOP1 has been performed." (PMID 34603446, 2021). "So far, the study of BOP1 in cancers has been limited, and comprehensive data are not available." (PMID 32167616, 2020).
tumor (16 papers, 2015 to 2025). "Overall, our findings show that BOP1 expression is linked to the tumor microenvironment, immune cell infiltration, MSI, and TMB; impacts patient prognosis; and gives new insights into immunotherapy and immunosuppressive drug development." (PMID 34603446, 2021). "In human CRC clinical samples, BOP1 is overexpressed in cancer cells compared to normal adjacent epithelial cells and represents a biological marker associated with tumor progression and formation of distant metastases." (PMID 33120992, 2020). "Besides, high expression of BOP1 was associated with tumor grade and poor survival, acting as an independent prognostic factor for HCC patients." (PMID 33575212, 2020). "The identification of prognostic markers through Cox regression and Lasso regression further highlighted the significant role of the risk genes BOP1, CTBP1, DSE, SRPK1, and PMSD10, which were upregulated in high mRNAsi tumor cells." (PMID 40963856, 2025). "The analysis revealed that risk genes (BOP1, CTBP1, DSE, SRPK1, and PMSD10) were significantly upregulated in tumor samples, whereas the protective gene HACD4 was highly expressed in normal samples." (PMID 40963856, 2025). "By integrating both single-cell and bulk RNA-seq data, we identified six key prognostic genes (BOP1, CTBP1, DSE, PMSD10, SRPK1, and HACD4), which were associated with poor prognosis and tumor cell proliferation." (PMID 40963856, 2025). "MYBL1, VCPIP1, MYC and BOP1 transcript expression levels were assessed in MCF10A non-tumor triple negative cell lines compared to Hs 578T, BT-549 and MDA-MB-231 TNBC cell lines." (PMID 38473786, 2024). "We also BOP1 expression is related to more advanced pathological grades (P = 0.0096) and tumor sites (P = 0.0272)." (PMID 35222794, 2022). "We investigated the relation between BOP1 expression and DNA methylation, tumor microenvironment (TME), microsatellite instability (MSI), tumor mutational burden (TMB), and immune checkpoints." (PMID 34603446, 2021). "Our results also indicated that the BOP1 promoter methylation level was positively related to survival time in tumor patients." (PMID 34603446, 2021). "We also analyzed the relationship between BOP1 expression and DNA methylation, tumor microenvironment (TME), microsatellite instability (MSI), tumor mutational burden (TMB), and immune checkpoints." (PMID 34603446, 2021). "Given that alterations in BOP1 affecting its expression level, we explored the relationship between BOP1 alterations and prognosis of tumor patients." (PMID 34603446, 2021). "Our results showed that BOP1 expression is correlated with tumor microenvironment involving immune regulation, DNA damage repair, and EMT." (PMID 34603446, 2021). "BOP1 has been reported to participate in various tumor biological processes, such as tumorigenesis, epithelial‐to‐mesenchymal transition, migration, and drug resistance." (PMID 32167616, 2020). "Previous studies have indicated that BOP1 can regulate tumor development by various known regulatory pathways." (PMID 32167616, 2020). "Compared with that in paired adjacent normal tissue samples, BOP1 expression was significantly upregulated in tumor tissues." (PMID 32167616, 2020). "Block of proliferation 1 (BOP1) regulates tumorigenesis, epithelial‐to‐mesenchymal transition, migration, metastasis, and drug resistance in several tumor types." (PMID 32167616, 2020). "Increased mRNA fold change of BOP1 was significant in tumor tissues with copy number gains (P = 0.024) as well as in those without (P < 0.001)." (PMID 26360582, 2015). "BOP1 expression was increased in 4 kind of tumor cell lines compared with the normal group." (PMID 35222794, 2022). "Collectively, these finding suggested BOP1 was a possible driver for the tumor metastasis." (PMID 35222794, 2022). "It showed that all tumor cell lines had higher BOP1 mRNA expression than GSE-1 cells." (PMID 35222794, 2022).
tumor (continued). "We found that the BOP1 expression level is significantly associated with the expression of these immune checkpoint genes in the majority of malignancies; it suggests that BOP1 might be used as a potential biomarker to guide tumor immunotherapy." (PMID 34603446, 2021). "BOP1 expression was significantly upregulated in CRC tumor tissues." (PMID 32167616, 2020). "These clinical results showed that BOP1 overexpression in CRC patients might be associated with CRC aggressiveness, especially tumor metastasis." (PMID 32167616, 2020). "Overall, BOP1 overexpression in CRC patients might be associated with CRC aggressiveness, especially tumor metastasis." (PMID 32167616, 2020). "Moreover, BOP1 expression might be used as a potential prognostic marker in patients with tumor metastases." (PMID 34603446, 2021). "We calculated the TMEscore and differentially expressed TME signatures according to BOP1 expression in 33 types of tumor, and we investigated the correlation between BOP1 expression and TMEscores, and relevant biological processes were determined in each tumor." (PMID 34603446, 2021). "Functional validation experiments confirmed that BOP1, CTBP1, DSE, PMSD10, and SRPK1 promote LMS cell migration, invasion, and colony formation, further highlighting their role in tumor progression." (PMID 40963856, 2025). "These functional experiments provide strong evidence that BOP1, CTBP1, DSE, PMSD10, and SRPK1 play key roles in LMS progression, acting as potential therapeutic targets to limit tumor invasion and metastasis." (PMID 40963856, 2025). "We have detected the expression of BOP1 mRNA and protein in a normal gastric epithelial cell line (GSE-1) and 4 tumor cell lines (HGC-27, N87, MGC-803 and BCG-823)." (PMID 35222794, 2022). "RAD21, BOP1, POLR2E, and PRKDC were mainly expressed in tumor cells, RIPK2 was mainly expressed in monocytes, MAP2K2 was mainly expressed in tumor cells and macrophages, NBN was mainly expressed in macrophages and monocytes, and GPX4 was mainly expressed in tumor cells and T cells." (PMID 36212155, 2022). "The IHC staining results also showed that normal breast, lung, ovary, rectum, and endometrium tissues with weak or no BOP1 IHC staining intensity, while corresponding tumor tissues with more stronger staining intensity." (PMID 34603446, 2021). "In the present study, we performed IHC analysis of both tumor tissue samples and matched adjacent nontumor tissue samples to analyze the expression level of BOP1 in patients with CRC." (PMID 32167616, 2020). "However, the PUF60, BOP1, and E2F1 genes were found to be significantly over-expressed in tumor tissues with copy number gains." (PMID 26360582, 2015). "While tumor weight did not correlate with BOP1 level (P = 0.2393)." (PMID 35222794, 2022). "To examine BOP1 protein expression in CRC tissues, we performed IHC analysis on both tumor tissue samples and matched adjacent nontumor tissue samples." (PMID 32167616, 2020). "In contrast to PUF60, the BOP1 and E2F1 were found to be over-expressed in tumor tissues with copy number gains as well as in those without." (PMID 26360582, 2015).
BOP1 also shares sentences with these, for which no sentence is quoted: cervical cancer (1 paper); Cirrhosis (1); esophageal cancer (1); hyperandrogenism (1); infarction (1); infection (1); lung adenocarcinoma (1); meningioma (1); neuroblastoma (1); Pan (1); paraganglioma (1); pheochromocytoma and (1); polycystic ovary syndrome (1); prostate tumors (1); sarcoma (1); testicular germ cell tumor (1); thyroid carcinoma (1).